BAP1 (BRCA1 associated deubiquitinase 1)
Diseases named in the same sentence as BAP1 in open-access papers (continued):
Sharing a sentence is not in itself a finding about the gene and the disease.
mesothelioma (continued). "Rucaparib demonstrated higher efficacy in a phase II trial, when given to patients with BAP1-negative or BRCA1-negative mesothelioma with a disease control rate of 58% at 12 weeks (95% CI 37–77; 15 of 26 patients), and at 24 weeks was 23% (9–44; six of 26 patients)." (PMID 37686585, 2023). "In mechanism, ovarian ATs may not be related to BAP1 or CDKN2A/p16 mutations, which are characteristic of most mesotheliomas." (PMID 36572896, 2022). "No mesotheliomas were found in BAP-1 +/− mice that had not been exposed to asbestos." (PMID 36553016, 2022). "However, recent pre-clinical studies showed that the BAP1 status does not determine the sensitivity to PARP inhibitors in patient-derived mesothelioma cell lines, which is surprising and in contrast with previous observations." (PMID 34070352, 2021). "Moreover, mesotheliomas arose in the absence of alteration of Bap1 and Nƒ2, as in HMM, consistent with a role of other pathways affected by the genes mutated at low frequency, or epigenetic mechanism." (PMID 30060470, 2018). "Rare families susceptible to uveal and cutaneous melanoma and non-melanoma cancers such as mesothelioma and renal cell carcinoma have also been described with inactivation of BRCA1 associated protein 1 (BAP1), a gene also frequently somatically mutated in uveal melanomas." (PMID 26433962, 2016). "However, whilst this was seen in BAP1 knockout chicken lymphoma cells, no synthetic effects were found in human mesothelioma cells emphasizing the importance of cellular context." (PMID 25970771, 2015). "In addition, we recommend that testing of BAP1 should not be conducted routinely in CM families but should be reserved for families with CM and uveal melanoma, or mesothelioma." (PMID 25803691, 2015). "As for NF2, although many NF2 patients reach the age of morbidity for mesothelioma onset, the development of mesothelioma has not specifically been reported, suggesting that NF2 germline mutation is unlikely to be a predisposing condition for familial PM development like BAP1." (PMID 40725095, 2025). "We therefore propose that BAP1 inactivation causes mitotic defects through BRCA1-dependent and independent mechanisms revealing novel routes by which mesothelioma cells lacking BAP1 may acquire genome instability and exhibit altered responses to microtubule-targeted agents." (PMID 36550359, 2023). "Supporting the idea that BAP1 mutant cancers actually confers loss of PcG repression rather than the previously assumed hyperactivation of PRC1 and PRC2 activities, is the lack of response of BAP1 mutant mesothelioma patients to the EZH2 inhibitor Tazemetostat." (PMID 36105358, 2022). "However, the sensitivity of mesothelioma cells to PARP inhibitors may be independent of the BAP1 status, warranting further studies to investigate the BAP1/PARP intersection." (PMID 33072611, 2020). "Although both BAP1 and USP1 were capable of deubiquitinating FANCD2 in vitro, USP1 suppression in mesothelioma cells did not provide clear biochemical evidence of altered FANCD2 ubiquitination." (PMID 42069682, 2026). "In contrast, depletion of FANCD2 suppressed cell proliferation irrespective of BAP1 status, underscoring the essential role of FANCD2 in mesothelioma cell survival." (PMID 42069682, 2026). "Recent studies have indicated that the lack of BAP1 and MTAP expression, along with the homozygous deletion of CDKN2A identified through FISH, can effectively differentiate mesothelioma from benign proliferations." (PMID 40432917, 2025). "Therefore, although many NF2 patients reach the age of morbidity for mesothelioma onset, the development of mesothelioma has not specifically been reported, suggesting that NF2 germ line mutation is unlikely to be a predisposing mutation for familial mesothelioma development like BAP1." (PMID 37180489, 2023). "Here, we demonstrated similar roles for BAP1 in controlling MAD2L1 expression and BUBR1 localization to kinetochores in non-drug treated mesothelioma cells." (PMID 36550359, 2023).
mesothelioma (continued). "Mesothelioma cell lines NCI‐H2373 and Y‐MESO‐14 served as positive and negative control for BAP1 protein expression, respectively." (PMID 34706158, 2022). "In addition, although BAP1 loss and CDKN2A/p16 homozygous deletion have emerged as reliable markers for the differential diagnosis of benign mesothelial proliferation versus mesothelioma, they were revealed not to be appropriate for distinguishing mesothelioma from other malignant tumors." (PMID 36552912, 2022). "Another two cases, both with a predominant pleural tumor mass (patient 4 and 7), were initially classified as mesothelioma, although all mesothelial markers such as calretinin, WT1, D2-40 and CK5/6 tested negative and BAP-1 and MTAP were retained." (PMID 35864317, 2022). "The results revealed biallelic gene inactivation of SETD2, BAP1, PBRM1, and SMARCC1, suggesting that the mesothelioma genome is affected by minute deletions that are non-detectable by singular NGS-based approaches or commercial array CGH." (PMID 30060501, 2018). "The relationship between BAP1 expression and HDAC inhibitor sensitivity has not previously been explored in mesothelioma." (PMID 25970771, 2015). "Similarly, cohorts of Bap1+/− mice and WT littermates in 129/Sv or C57BL/6 backgrounds were followed until the end of life, and no spontaneous mesotheliomas were observed." (PMID 40867321, 2025). "However, the knockout or overexpression of BAP1 did not significantly affect the expression of PD-L1 in the pancreatic cancer cell line (PANC-1), renal cancer cell line (OS-RC-2) and mesothelioma cell line (H2810)." (PMID 39350280, 2024).
uveal melanoma (304 papers, 2010 to 2026). A melanoma derived from melanocytes of the uveal tract. "PURPOSE: BAP1-tumor predisposition syndrome (BAP1-TPDS) is associated with four main cancers: uveal melanoma, cutaneous melanoma, malignant mesothelioma, and renal cell carcinoma." (PMID 41670784, 2026). "In the second cohort, which included 80 patients with uveal melanoma, we observed a significantly worse disease‐specific survival in cases of BAP1‐mutated uveal melanoma." (PMID 41262171, 2025). "The deubiquitinating enzyme (DUB) BAP1, BRCA1-associated protein 1, is a major tumor driver and metastasis suppressor in uveal melanoma (UM), the most common primary cancer of the eye." (PMID 41022584, 2025). "Uveal melanomas with a loss of chromosome 3p and a BAP1 mutation, typically also showing chromosome 8q copy number increases, have the poorest prognosis." (PMID 40240901, 2025). "Loss-of-function mutations within subunits of the BAP1 complex were observed in several types of cancer, such as leukemia and uveal melanoma, supporting a potential tumor-suppressive function of BAP1." (PMID 39817454, 2025). "This is notably due to BAP1 loss causing global increases in H2AK119ub1, which occurs frequently in uveal melanoma (~45%)." (PMID 40000790, 2025). "In uveal melanoma, high BAP1 expression has been significantly associated with a favorable clinical prognosis." (PMID 40843116, 2025). "These BAP1 gene mutations have been mainly associated to uveal melanoma and to an increasing number of cancers, including mesothelioma, meningioma, and renal cell carcinoma." (PMID 40869905, 2025). "For instance, recurrent loss-of-function mutations within BAP1 have been detected in uveal melanoma, indicating a potential tumor-suppressive function of BAP1 in this specific cancer type." (PMID 39817454, 2025). "A similar analysis of RPPA data from uveal melanoma (UM) tumors from TCGA (UVM-TCGA) also showed that tumors with BAP1 mutations have a decrease in SRC phosphorylation at Y527." (PMID 40754831, 2025). "It has been demonstrated that the dysregulation of BAP1 and its associated factors are involved in the tumorigenesis of many different cancer types, including uveal melanoma, breast cancer, prostate cancer, leukemia, and lung cancer." (PMID 39817454, 2025). "We enrolled a consecutive cohort of 270 Finnish patients with uveal melanoma (UM) and analyzed them for pathogenic germline variants in 19 genes associated with UM, BAP1, or renal cell carcinoma (RCC)." (PMID 39344744, 2025). "For instance, in BAP1-related uveal melanoma, mutations in genes encoding components of the Gq signal transduction pathway are also needed to cause the disease." (PMID 40867321, 2025). "BAP1 gene mutations have been identified in various tumor types and acknowledged as a critical event in metastatic uveal melanoma, but their role in non-uveal melanoma remains inadequately characterized." (PMID 38903495, 2024). "BAP1 inactivation is strongly linked to a higher metastatic risk and poor prognosis in uveal melanoma, mutated in 84% of metastatic cases." (PMID 38903495, 2024). "While in uveal melanoma and ccRCC, BAP1 loss of expression is associated with immunosuppressive microenvironment." (PMID 39350280, 2024). "In 34–45% of uveal melanoma cases, one of the BAP1 alleles is displaced from chromosome 3, which deactivates this gene." (PMID 38540335, 2024). "Approximately 50% of all uveal melanomas express a mutated inactive form of BAP1, with the majority of metastatic disease having BAP1 mutations." (PMID 38758815, 2024). "Primary bilateral uveal melanoma is an exceptionally rare condition, which in some instances can be attributed to germline mutations in the BAP1 gene." (PMID 38892746, 2024). "In summary, this is the first meta-analysis of driver mutations in uveal melanoma, showing that BAP1 mutations are linked to an increased risk of metastatic disease in uveal melanoma, while no such association was observed with GNAQ/GNA11 and SF3B1 mutations." (PMID 39061150, 2024).
uveal melanoma (continued). "On the other hand, rare uveal melanoma is associated with the inheritance of the pathogenic BAP1 variant." (PMID 38540335, 2024). "Mutations in the BRCA-1 associated protein 1 (BAP1) gene were recognized as relevant in various cancer types, including uveal melanoma, mesothelioma and renal cell carcinoma." (PMID 38903495, 2024). "Genetic analyses were conducted on tumor samples from 88 patients with uveal melanoma (UM), 6 of whom carry pathogenic germline variants in BAP1." (PMID 39378214, 2024). "Almost half of all uveal melanomas express a mutated inactive form of BAP1; mutation of a single allele of BAP1 is associated with tumor progression and metastatic spread." (PMID 38758815, 2024). "Persons with a single germline mutant allele of BAP1 are also pre-disposed to developing uveal melanoma." (PMID 38758815, 2024). "Non-uveal melanomas frequently harbored more than one BAP1 mutation (n=54, 45.8%), while only 3 samples of uveal origin (27.3%) harbored two or more." (PMID 38903495, 2024). "In fact, BAP1 mutations are noted in 47% of all uveal melanomas and 84% of patients with metastatic uveal melanoma, indicating a worse prognosis." (PMID 39001457, 2024). "BRCA1-associated protein 1 (BAP1) is a tumor suppressor gene that is frequently mutated in metastatic uveal melanomas in the late stages of melanomagenesis." (PMID 37370834, 2023). "Uveal melanoma-related genes (BAP1, SF3B1, GNAQ/11) can also be mutated in CMs, albeit infrequently." (PMID 37761808, 2023). "Detecting a germline mutation of BAP1 not only indicates an increased risk of uveal melanoma (UM), but also suggests a potential association with other types of tumors." (PMID 37628989, 2023). "BAP1 Germline mutations are associated with other malignant tumors such as uveal melanoma and renal cell carcinoma, collectively known as BAP1 tumor predisposition syndrome." (PMID 37461124, 2023). "An association between loss of BAP1 expression and increased infiltration with TAMs has previously been reported in uveal melanoma." (PMID 36562826, 2023). "Alterations in epigenetic regulations contribute to this phenotype, as evidenced by the restoration of melanocyte differentiation when uveal melanoma cells with mutated BAP1 are treated with histone deacetylase (HDAC) inhibitors." (PMID 37370834, 2023). "They differ, for instance, in the oncogenic driver mutations, mainly alterations in MAPK signaling in cutaneous melanoma and alterations in GNAQ/GNA11 signaling or the BRCA1-associated protein BAP1 in uveal melanomas." (PMID 37577930, 2023). "Combination of trametinib and cerivastatin were synergistic in vitro and in vivo in BAP1 mutated and chromosome 3 monosomic uveal melanoma cell lines." (PMID 36765842, 2023). "As for the BRCA1 associated protein 1 (BAP1), it plays a crucial role in cell division and DNA repair, with reported mutations in around 3% of uveal melanomas, especially in patients with metastases." (PMID 37568588, 2023). "The BAP1 gene mutations frequently occur in uveal melanoma and this nonsense mutation enables metastasis by upregulating cell-cell adhesion factors necessary for the cancer cells to breach the basement membrane." (PMID 38090659, 2023). "Clinically, systematic analyses show that although BAP1 loss of function is associated with worse prognosis in uveal melanoma and renal clear cell carcinoma (RCCC), it predicts better prognosis in patients with MPM." (PMID 36669126, 2023). "In the context of cancers, such as uveal melanoma, BAP1 loss has been proposed as a driver of characteristics associated with cancer stem cells." (PMID 36740402, 2023). "Other factors include a family history of cutaneous and uveal melanoma, dysplastic nevus syndrome, ocular or oculodermal melanocytosis—namely Nevus of Ota—and mutation of breast cancer 1 (BRCA1) associated protein 1 (BAP1)." (PMID 37628989, 2023).
uveal melanoma (continued). "Two patients had a history of renal cell cancer diagnosed prior to uveal melanoma but only one of these two patients was heterozygous for a pathogenic BAP1 germ-line mutation." (PMID 35920959, 2023). "Risk factors for the development of uveal melanoma include fair skin, light eye color (green or blue), welding, congenital ocular melanocytosis, dysplastic nevi, and BAP1- tumor predisposition syndrome." (PMID 37504330, 2023). "Germline inactivation of BAP1 confers an increased risk for developing cutaneous and uveal melanoma, mesothelioma, renal cell carcinoma, and breast cancer, albeit to a lesser extent." (PMID 37813891, 2023). "Recent basic and clinical research has figured out, that Uveal melanoma was characterized by a series of genetic mutations like the Gq pathway alterations, the gene BAP1, splice, and EIF1AX mutations (also known as the BSE event)." (PMID 36920166, 2023). "Inactivating somatic mutations have been identified in BAP1 in metastasizing uveal melanoma (UM) at a frequency of 84%, with one affected individual carrying a germline mutation." (PMID 37009801, 2023). "During their lifetime, all carriers of inherited heterozygous BAP1-inactivating mutations develop at least one cancer and often multiple cancers, mostly malignant mesothelioma and uveal melanoma (called BAP1 cancer syndrome)." (PMID 36754982, 2023). "Mutations of the ubiquitin carboxyl-terminal hydrolase gene (BAP1) and loss of chromosome 3 are strictly related to uveal melanoma progression, with monosomy of chromosome 3 a predictor for ulterior metastases." (PMID 35741122, 2022). "Two studies identified somatic BAP1 (BRCA1-Associated Protein 1) mutations in approximately 5% of cutaneous melanoma and in 30–40% of primary uveal melanoma." (PMID 35563772, 2022). "Dysregulations and mutations within the BAP1 gene have been identified as drivers in many human cancers, such as uveal melanoma, mesothelioma, clear-cell renal cell carcinoma, leukemia, and breast cancer." (PMID 35194152, 2022). "Somatic bi-allele mutation resulting in BAP1 loss has been associated with improving prognosis and it has been observed in nearly 60% of malignant pleural mesothelioma in uveal melanoma and other tumors." (PMID 35204459, 2022). "Genetic features as fair-skin, light-coloured eyes, ocular melanocytosis besides germline mutations in BAP1 gene, increase the odds of developing uveal melanoma." (PMID 36318367, 2022). "BAP1-deficient uveal melanoma has a poor prognosis, particularly in cases due to somatic inactivation." (PMID 35381901, 2022). "Three studies have underlined a higher risk of hereditary cancers, such as uveal melanoma, malignant mesothelioma (pleural and peritoneal), renal cell carcinoma and cutaneous melanoma, in patients with a germline mutation of BAP-1." (PMID 36553016, 2022). "In alternative to BAP1, metastatic uveal melanomas often present mutations of SF3B1, which are associated with a longer disease-free survival." (PMID 35409195, 2022). "In uveal melanoma samples, these alterations were associated with a higher metastatic risk in comparison to wild type tumors and those with germline BAP1 mutations." (PMID 35563772, 2022). "We investigated which of these options was likely to have occurred in uveal melanoma and other cancers with BAP1 mutations." (PMID 36077643, 2022). "In turn, monosomy 3 is associated with mutations in the tumor suppressor gene BAP1, located on the short arm of chromosome 3 and is associated with uveal melanoma." (PMID 35413810, 2022). "A cohort of 100 uveal melanomas from the United Kingdom was profiled for biomarkers, including BAP1 immunostaining, BAP1 sequence variants, LOH3, and chromosome 8q gain." (PMID 36077643, 2022). "Individuals carrying germline monoallelic mutation in BAP1 show a high frequency of malignant mesothelioma (MM), uveal melanoma (UM) and clear cell renal cell carcinoma (ccRCC)." (PMID 36318367, 2022).